ATP10A (ATPase phospholipid transporting 10A (putative))
Diseases named in the same sentence as ATP10A in open-access papers:
ATP10A is named in the same sentence as 32 diseases in open-access papers, as found by Europe PMC text mining. Sharing a sentence is not in itself a finding about the gene and the disease. The quoted sentences say what the papers report.
Obesity (14 papers, 2011 to 2024). Accumulation of substantial excess body fat. "The mouse ATP10A gene (also called ATP10C) is linked to diet-induced obesity and type II diabetes phenotypes, and an ATP10D mutation shows linkage to a fat-prone phenotype in certain strains of mice." (PMID 24957965, 2012). "We also observe previously identified obesity associated genes, such as Zfp69, Slc24a3, Qpctl, Atp10a, and Folr2." (PMID 22471599, 2012). "However, another member of the P4 ATPase family, atp10a, has been shown to be important for the biogenesis and/or membrane-directed trafficking of Glut4 receptors, and loss-of-function of atp10a induces IR and obesity in mice." (PMID 26818947, 2016). "Atp10a (also named Atp10c) is linked to diet-induced obesity and type II diabetes in mice." (PMID 22912588, 2012). "Even though ATP11A’s involvement in obesity and T2D is unknown, there is evidence that deficient expression of some P4 ATPase family members, such as ATP10C and ATP10A, affects insulin-stimulated mobilization of GLUT4 vesicles to the plasma membrane or the regulation of insulin signaling." (PMID 36535927, 2022). "Previous reports suggested a role for murine ATP10A in diet-induced obesity, insulin resistance, and dyslipidemia and these phenotypes were more severe in female mice." (PMID 38172157, 2024). "Previous studies in mouse models have shown that P4-ATPases fulfil multiple important physiological functions and that another flippase, ATP10A, is involved in type 2 diabetes and diet-induced obesity." (PMID 35807162, 2022). "Heterozygous deletions of Atp10a in mice lead to diet-induced obesity, insulin resistance, and nonalcoholic fatty liver disease." (PMID 30777014, 2019). "Our findings are in good agreement with reports demonstrating the role of ATP10A (formerly ATP10C), another class 5 P4-type ATPase, in diet-induced obesity, T2D and insulin-stimulated glucose uptake." (PMID 28542499, 2017). "Altogether, these results indicate that Atp10A deficiency does not alter the development of diet-induced obesity under the conditions tested." (PMID 38172157, 2024). "Mice heterozygous for the P4-ATPase Atp10a (also named Atp10c) develop insulin resistance, hyperlipidemia and are hyperinsulinemic and provide a model for type-2 diabetes mellitus and diet-induced obesity." (PMID 23579954, 2013). "Moreover, mRNA expression levels of a canine ATP10A orthologue in visceral adipose tissue were found to be five times higher in obese dogs in comparison with lean dogs, suggesting an involvement of ATP10A in response to diet-induced obesity." (PMID 23579954, 2013). "Interestingly, a lack of ATP10A activity in adulthood is related to obesity in humans and SRGAP3 expression is known to be influenced by its DNA methylation status." (PMID 33005172, 2020).
Insulin resistance (9 papers, 2010 to 2024). Increased resistance towards insulin, that is, diminished effectiveness of insulin in reducing blood glucose levels. "SNPs in ATP10A have been shown to correlate with an increased risk of insulin resistance in a cohort of African Americans." (PMID 38382846, 2024). "Genetic association studies have linked ATP10A and closely related type IV P-type ATPases (P4-ATPases) to insulin resistance and vascular complications, such as atherosclerosis." (PMID 38172157, 2024). "A genome-wide association study reported a correlation between Atp10A variants and increased risk for developing insulin resistance and mice harboring large, irradiation-induced chromosomal deletions, that included Atp10A, exhibited worsened metabolic profiles." (PMID 38415274, 2024). "This site is also 122,184 bp away from the ATP10A gene, which has been suggested to be a possible candidate gene driving a GWAS signal identified for insulin resistance in the African American cohort of the HyperGEN study." (PMID 25902833, 2015). "Additionally, GWA studies have implicated ATP10A and ATP10D in insulin resistance, HDL homeostasis, and atherosclerosis, suggesting that these flippases influence liver metabolism." (PMID 38382846, 2024). "This could indicate that an altered epigenomic regulation of ATP10A may determine the degree of insulin-resistance in humans." (PMID 23579954, 2013). "Studies of mice carrying a radiation-induced large deletion proximal to the 3′-end of Snrpn to the p locus that included Atp10a, indicated that Atp10a may have an important role in insulin resistance and glucose metabolism." (PMID 20808828, 2010). "End-point mapping of a nested deletion series implicated Atp10A in the metabolic defects but whether an Atp10A-specific knockout is sufficient to cause insulin resistance has not been determined." (PMID 38172157, 2024). "Although ATP10A has not been identified as a risk gene for type 2 diabetes in Caucasian Europeans, the genomic region encompassing ATP10A was identified as a risk locus in a genome-wide association study (GWAS) of insulin resistance in an African American cohort." (PMID 23579954, 2013). "With the exception of ATP8B4 (Alzheimer’s disease) and ATP10A (insulin resistance in African Americans), thus far none of the human P4 ATPases have been identified as risk genes in GWAS." (PMID 23579954, 2013).
type 2 diabetes (8 papers, 2011 to 2024). "ATP10A belongs to a family of aminophospholipid-transporting ATPases and has been associated with type 2 diabetes in mice." (PMID 21901158, 2011). "ATP10A was suggested to be imprinted and associated with type 2 diabetes." (PMID 21904626, 2011). "Interestingly, there is evidence indicating a connection between metabolic status and the expression of ATP10A in spermatozoa; indeed, type 2 diabetic patients exhibit differential DNA methylation patterns of ATP10A in human spermatozoa, compared to healthy individuals." (PMID 38415274, 2024).
autism (7 papers, 2008 to 2023). Persistent deficits in social interaction and communication and interaction as well as a markedly restricted repertoire of activity and interest as well as repetitive patterns of behavior. "For other genes, such as SNRPN, CYFIP1, and ATP10A, a few SNPs or haplotypes were found to be nominally associated with autism in Europeans20,24–26." (PMID 30108208, 2018). "Moreover, even PWS and AS specific genes that lie in the BP2-BP3 PWS/AS region, such as, MAGEL2, SNRPN, UBE3A, and ATP10A are also significantly co-associated with autism (Malacards.org; SFARI.org)." (PMID 32384786, 2020). "Moreover, our study demonstrated that rs4906902 in GABRB3 and rs4906771 in ATP10A were significantly associated with autism under the recessive model, although these positive results were not replicated in ASD subset of PGC." (PMID 30108208, 2018). "Additionally, rs4906902 in GABRB3 and rs4906771 in ATP10A exhibited significant association with autism under the recessive model." (PMID 30108208, 2018). "Moreover, GABRB3 and ATP10A located on chromosome 15q11-q13 might increase risk for autism in Chinese Han population." (PMID 30108208, 2018). "Even the GABRB3 gene that is distal to the ATP10A gene is a SFARI (SFARI.org) recognized autism gene (Malacards.org; SFARI.org)." (PMID 32384786, 2020). "Moreover, 7 SNPs (rs3812922 in NIPA2, rs8037745 in SNRPN, rs4906771 and rs1345098 in ATP10A, rs12438141, rs1863467, and rs4906902 in GABRB3) displayed nominal association with autism under the additive model in our samples (p < 0.05)." (PMID 30108208, 2018). "Cases I and II, are carriers of the same duplication on chromosome 15 [15q11.2q13.1(SNRPN,UBE3A,ATP10A,GABRB3,OCA2) x3], both have severe autism but with different levels of cognition." (PMID 28174603, 2017).
Angelman syndrome (3 papers, 2016 to 2020). A neurogenetic disorder characterized by severe intellectual deficit and distinct facial dysmorphic features. "We note that the region spans a cluster of imprinted genes and is homologous to human Chr15 that contains the genes causing Prader-Willi and Angelman syndromes and that imprinting of some of our candidate genes, including Atp10a, in mice have been described." (PMID 28837567, 2017).
dyslipidemia (3 papers, 2018 to 2024). "Together, these results show that Atp10A deficiency causes female-specific dyslipidemia and changes to lipoprotein metabolism after HFD feeding." (PMID 38172157, 2024). "Atp10A deficient female mice exhibit dyslipidemia characterized by elevated plasma FFA, cholesterol, TG, and alterations in the size and lipid content of both VLDL and HDL." (PMID 38172157, 2024). "It will be interesting to determine if the sexually dimorphic dyslipidemia in the Atp10A KO mice is linked to dysregulation of PEMT or to choline deficiency." (PMID 38172157, 2024). "Atp10A deficient mice display female-specific diet-induced dyslipidemia, broad changes to lipid metabolism, and disruptions in liver insulin signaling." (PMID 38172157, 2024). "We have shown that ATP10A is required to maintain lipid homeostasis and liver insulin sensitivity with HFD feeding, therefore, a therapeutic that acts as an ATP10A agonist could help treat diseases that cause dyslipidemia and hepatic insulin resistance." (PMID 38172157, 2024). "We recently produced an Atp10A exon 2 knockout (KO) mouse model and found that Atp10A−/− mice exhibit sex-specific diet-induced dyslipidemia." (PMID 38415274, 2024). "This study reveals a requirement for ATP10A in protecting female mice from dyslipidemia after HFD feeding." (PMID 38172157, 2024). "To get a broader view of the dyslipidemia in the plasma of female Atp10A−/− mice, we performed mass spectrometry-based untargeted lipidomics on plasma from female Atp10A−/− and Atp10A+/+ littermates after 12 weeks on HFD after a 5 h fast." (PMID 38172157, 2024). "We previously showed that female Atp10A deficient mice fed a high fat diet exhibit dyslipidemia, but the male mice do not." (PMID 38415274, 2024).
atherosclerosis (2 papers, 2022 to 2024). A disease characterized by the build-up of fatty material and calcium deposition in the arterial wall resulting in partial or complete occlusion of the arterial lumen. "SMC1.2, strongly expressed ITGA8, required for maintenance of SMC contractile phenotype, and ATP10A, suggesting vascular stiffness and increasing diastolic dysfunction Methylation of the ATP10A locus in SMC decreases with age and atherosclerosis." (PMID 35926050, 2022).
acute lymphoblastic leukemia (1 paper, 2024). Leukemia with an acute onset, characterized by the presence of lymphoblasts in the bone marrow and the peripheral blood. "Recurrent aberrations of 14 genes were detected in patients with childhood acute lymphoblastic leukemia (ALL) who subsequently relapsed, including deletions or uniparental isodisomies of ATP10A." (PMID 38382846, 2024).
albinism (1 paper, 2008). A congenital disorder characterized by partial or complete absence of melanin pigment in the eyes, hair, or skin. "These genomic probes except P2 were generated by PCR amplification from genomic DNAs and are located close to the CpG island of CYFIP1 (P1), the 3'-end of the UBE3A gene (P3), the CpG island of ATP10A (P4), and the CpG island of the P locus for albinism." (PMID 18226259, 2008).
asthenozoospermia (1 paper, 2024). "The phenotypes caused by Atp10A deficiency, such as reduced testes size, oligozoospermia, asthenozoospermia, and the observed histopathological changes in the testes and vas deferens, emphasize its importance in the maintenance of male-specific fertility." (PMID 38415274, 2024). "The Atp10A deficient male mice exhibit smaller testes, reduced sperm count (oligozoospermia) and lower sperm motility (asthenozoospermia)." (PMID 38415274, 2024). "Altogether, Atp10A deficiency results in small testes, oligozoospermia, and asthenozoospermia." (PMID 38415274, 2024).
cervical cancer (1 paper, 2023). A primary or metastatic malignant neoplasm involving the cervix. "In a genome-wide DNA methylation profiling study of cervical cancer stages, in which CpG sites whose state of methylation correlated with lesion grade were assessed, ATP10A was short-listed as a gene associated with the progression from normal through precancerous lesions and cervical cancer." (PMID 37686603, 2023).
chronic lymphocytic leukemia (1 paper, 2024). "A similar study to identify mutations enriched before and after therapy in patients with relapsed chronic lymphocytic leukemia (CLL) found that ATP10A mutations were enriched after relapse." (PMID 38382846, 2024).
Infertility (1 paper, 2024). "To explore the molecular mechanisms underlying Atp10A deficiency-induced infertility, we examined the levels and phosphorylation status of key proteins involved in gonadotropin signaling within the testes." (PMID 38415274, 2024). "There is also a need to determine if mutations in ATP10A could be potential risk factors for male-specific infertility in humans." (PMID 38415274, 2024). "Taken together, male Atp10A deficient mice exhibit infertility accompanied by elevated testosterone levels, which paradoxically could confer protection against metabolic disorders." (PMID 38415274, 2024). "Therefore, ATP10A deficiency alone is sufficient to cause the male-specific infertility phenotypes." (PMID 38415274, 2024). "Understanding the relationship between the observed infertility phenotypes, receptor-specific activation of the MAPKs and Akt, and the elevated levels of FSHR and LHR in the testes in Atp10A deficient mice requires further study." (PMID 38415274, 2024). "Our findings reveal that Atp10A deficiency leads to male-specific infertility, but does not perturb fertility in the females." (PMID 38415274, 2024). "Therefore, ATP10A deficiency alone is sufficient to cause the male-specific infertility phenotypes in mice and this suggests that the specific ATP10A substrate critical for male fertility might be PC and not GlcCer; because ATP10A flips both PC and GlcCer and ATP10D only flips GlcCer." (PMID 38415274, 2024).
male infertility (1 paper, 2024). The inability of the male to effect fertilization of an ovum after a specified period of unprotected intercourse. "To further understand the mechanism of how Atp10A deficiency causes male infertility, we measured hormones regulated by the HPG-axis, which controls the production and release of hormones involved in male reproductive function." (PMID 38415274, 2024).
melanoma (1 paper, 2023). A malignant, usually aggressive tumor composed of atypical, neoplastic melanocytes. "The whole-exome sequencing of 34 melanoma-prone families (119 cases) coupled with coexpression network analyses focused on modules associated with pigmentation processes introduced 36 genes (including ATP10A) as potential melanoma risk genes in the families." (PMID 37686603, 2023).
migraine (1 paper, 2020). "In our study, case patient R170 with an ATP10A variant (p.Ala881Val) presented with a confusional migraine following minor head injury." (PMID 32233732, 2020). "Although this person might not routinely suffer from migraine, a stressor (head injury) may have triggered the ATP10A risk allele effect." (PMID 32233732, 2020).
Pasteurella multocida infection (1 paper, 2023). "It was also found that P0910 and ΔOmpH in Pasteurella multocida infection activated the expression of ropE, HSPBP1, FERH, ATP10A, ABCA13, RRP7A, IL-10, IFN-γ, IL-17A, EGFR and dnaJ." (PMID 36977260, 2023).
prostate carcinoma (1 paper, 2021). A carcinoma that arises from epithelial cells of the prostate gland. "Three recurrent structural variants map to prostate cancer genes SH2B3, ATP10A and FOXA1." (PMID 34090332, 2021).
tumor (3 papers, 2021 to 2025). "Interestingly, several BBB-related transporters, including SLC2A1, ABCG2, ABCB1, SLCO1A2, and ATP10A were significantly decreased in ECs in tumor core." (PMID 34228647, 2021). "Of those, eight (HOXA3, HOXA5, ATP10A, SOX2, MIR922, ADAMTSL1, KHDRBS2, and LITD1) were hypermethylated in at least one LS tumor group like here in FAP normal, whereas NEDD4L, and FOXP1 were hypermethylated in LS carcinomas and here in LS normal." (PMID 40753397, 2025).
infection (1 paper, 2025). The state of being infected such as from the introduction of a foreign agent such as serum, vaccine, antigenic substance or organism. "P0910 and OmpH were also found to activate the expression of several genes, including ATP10A, upon infection with Pasteurella multocida in yak, and to be associated with female reproductive performance in Qaidam cattle." (PMID 40805107, 2025).
neurodevelopmental disorder (1 paper, 2022). A behavioral and cognitive disorder with onset during the developmental period that involves impaired or aberrant development of intellectual, motor, or social functions. "Instead, we identified several rare, likely pathogenic variants in seven genes implicated in neurodevelopmental disorders: KLHL17, TDO2, TRRAP, EIF3F, ATP10A, DICER1, and CDH15." (PMID 35743796, 2022).
ATP10A also shares sentences with these, for which no sentence is quoted: diabetes (2 papers); hyperlipidemia (2); metabolic disorders (2); nonalcoholic fatty liver disease (2); Prader-Willi syndrome (2); Alzheimer disease (1); carcinoma (1); cardiovascular diseases (1); migraine with aura (1); multiple myeloma (1); schizophrenia (1).